BRAF (B-Raf proto-oncogene, serine/threonine kinase)
Diseases named in the same sentence as BRAF in open-access papers (continued):
Sharing a sentence is not in itself a finding about the gene and the disease.
melanoma (continued). "In this patient the BRAF V600E mutation was identified in sorted CD146+/MCAM+/CD45− cells, whilst the mutation was not identified in sorted leukocytes (MCAM−/MCSP−/CD45+ cells) from the same specimen, confirming that MCAM+/MCSP+ cells identified by FCM indeed represent true melanoma cells." (PMID 38790134, 2024). "We suspect that the proportion of patients who are non-responders to BRAF inhibitor treatment contain patients with melanoma metastases that do not share the same BRAF status, wherein beside the BRAF mutated metastases further tumour spots with BRAF wild-type are present." (PMID 38127894, 2024). "Of note, immunotherapy was approved to treat people with advanced melanoma regardless of whether their tumors had BRAF mutation or not." (PMID 38339003, 2024). "CTHRC1 expression and the BRAF(V600E) mutation were positively correlated in these three types of tumors, with correlation coefficients of 0.139 in colon cancer (COAD, P < 0.05), 0.794 in thyroid cancer (THCA, P < 0.05), and 0.179 in melanoma (SKCM, P < 0.05), respectively." (PMID 39052013, 2024). "Our results support previous findings indicating the crucial involvement of EVs in melanoma progression, particularly emphasizing their greater contribution to metastasis formation compared to primary tumor growth, while also highlighting their implication in BRAF inhibitor resistance." (PMID 38778340, 2024). "Furthermore, several small-molecule and antibody-based inhibitors of IGF1R and the PI3K/AKT/mTOR pathway are currently being tested in the clinic, highlighting the potential translatability of combining these drugs with BRAF/MEK inhibitor therapy for the treatment of melanoma LMD." (PMID 38866016, 2024). "Decades of clinical trials have been dedicated to studying adjuvant therapy for melanoma, encompassing interventions such as high‐dose interferon‐α, immune checkpoint inhibitors (pembrolizumab, nivolumab), targeted therapy (dabrafenib‐trametinib for BRAF mutant melanoma), and chemotherapy." (PMID 38212945, 2024). "Unlike melanoma with a BRAF mutation, NRAS mutations are more resilient to treatment." (PMID 39519055, 2024). "In addition, many of these “spitzoid” tumors harbor BRAF mutations of the conventional melanoma pathway, and thus, should not fall into the Spitz pathway." (PMID 38247727, 2024). "In addition, it has been reported that statin treatment increases the vulnerability of PGC1α-suppressed BRAF-inhibitor resistant melanomas, and it may be effective against melanomas that gradually develop resistance to vemurafenib." (PMID 38540310, 2024). "Mutations in the BRAF gene may not directly cause melanoma, but the risk of melanoma increases with the addition of environmental factors." (PMID 38586368, 2024). "The available melanoma treatments range from conventional excisional surgery and chemotherapy to targeted systemic immunotherapy treatments or the combination of treatments (BRAF inhibitor, MEK inhibitor, anti-PD-1 monoclonal antibody, and anti-CTLA-4 monoclonal antibody)." (PMID 39519799, 2024). "Additionally, the polyclonal model of melanoma, in which subclones with different BRAF status may coexist in the same melanoma lesion, are supported by other studies." (PMID 38541077, 2024). "The presence of a BRAF mutation in a dysplastic nevus does not necessarily determine its transformation into melanoma, and it cannot be said with certainty if the dysplastic nevus will ever progress into any form of melanoma." (PMID 39200941, 2024). "The B-Raf proto-oncogene serine / threonine-protein (BRAF) V600E mutation has been focused on by researchers as a potential oncogenic factor in many types of cancer, such as papillary thyroid cancer, colorectal cancer, melanoma, and gliomas in both adult and pediatric populations." (PMID 39172230, 2024). "In some melanoma patients, BRAF copy number gains may be observed in addition to BRAF mutations." (PMID 39727691, 2024).
melanoma (continued). "In contrast, melanomas without BRAF V600E mutations showed a higher frequency of TPMs." (PMID 38371417, 2024). "Notably, melanoma patients with BRAF and NRAS mutations who have failed to respond optimally to agents like anti-PD-1 or anti-CTLA-4 antibodies have exhibited either partial response or long-stable disease (SD) after receiving TIL treatment." (PMID 38835341, 2024). "NRAS mutation in melanoma seems to be a prognostic marker of worse prognosis and more aggressive disease, with several studies indicating that OS for patients with NRAS-mutant melanoma is significantly lower compared to those with BRAF-mutant or NRAS/BRAF-wildtype tumor status." (PMID 39410017, 2024). "Additionally, the limited efficacy of RAF inhibitors in melanomas lacking BRAF mutations highlights the urgent need to develop alternative therapeutic approaches for this subgroup of patients." (PMID 39582535, 2024). "Furthermore, to validate our observations in melanoma cells lacking the BRAF mutation, in some experiments we examined the behavior of the MeWo cell line." (PMID 38338893, 2024). "However, it is important to keep in mind that mutations in the BRAF oncogene are not found in all melanoma patients, so we tested its combination with the conventional protein tumor biomarker S100B to identify high‐risk patients." (PMID 39387479, 2024). "In addition, one of the melanomas (MM1) was found to have a V600K mutation in the BRAF gene; this molecular finding specifically excludes the diagnosis of Spitz melanoma and, given the morphology, is best classified as Spitzoid melanoma." (PMID 38791877, 2024). "Although treating BRAF-mutant melanoma with BRAF and MEK inhibition has shown effectiveness despite notable treatment-related side effects, the scrutiny of drug-drug interactions impacting the toxicity linked to anti-BRAF/anti-MEK therapy has become imperative." (PMID 39582535, 2024). "There was hope that blocking BRAF kinase activity may benefit melanoma patients." (PMID 38686058, 2024). "In this study, we provide new insights into the prognostic value of ctDNA in resected stage III melanoma patients and emphasize the importance of serial ctDNA measurements for real-time surveillance of disease recurrence during adjuvant therapy, including BRAF/MEK targeted inhibitors." (PMID 39609824, 2024). "Given the reported roles of TAMs in BRAF mutant melanoma influencing tumor progression and response to targeted treatments, altering the macrophage protumour function may present a potential therapeutic strategy to improve melanoma treatments." (PMID 38533720, 2024). "Some investigations have reported mutually exclusive patterns, suggesting that TERT promoter mutations may represent an alternative pathway of telomerase activation in melanoma cases lacking BRAF or NRAS mutations." (PMID 37504268, 2023). "It should also be noted that in most cases, melanomas on the face do not show a BRAF mutation (the histology type is usually LMM), thus limiting treatment options, and often a patient’s comorbidities or lack of compliance prevent the use of systemic treatment altogether." (PMID 36902697, 2023). "Besides, ICIs may induce slow but more durable responses in a subset of patients with both BRAF-mutant and wild-type melanoma." (PMID 36995534, 2023). "Indeed, recently published data suggest that for patients with actionable BRAF mutations, prioritizing treatment with ICI as first line of treatment, followed by targeting BRAF/MEK only upon disease progression leads to survival gains for this subset of melanoma patients." (PMID 36674809, 2023). "BRAF (B-rapidly accelerated fibrosarcoma) and NRAS (N-Rat sarcoma virus) mutations, which are found in 50 and 20% of cases, respectively, are commonly responsible for dysregulation of the MAPK (mitogen-activated protein kinase)-proliferation signaling pathway in melanomas." (PMID 36747120, 2023).
melanoma (continued). "Similarly, pre-clinical data suggests chemotherapy plus TT may inhibit ATM-dependent DNA repair to kill melanoma cells, including in BRAF wild-type lines." (PMID 36988735, 2023). "Immunotherapy is used in stage II/III melanoma for patients without the BRAF mutation as the adjuvant treatment in addition to surgery, and it uses monoclonal antibodies directed against immune checkpoints, which comprise membrane receptors that inhibit the anti-tumor activity of T cells." (PMID 37371032, 2023). "But roles of IRGs in melanoma independently of BRAF V600E status are still unknown." (PMID 36704723, 2023). "This panel has addressed the lack of access to diagnosis and treatment for BRAF-mutated melanoma." (PMID 36998456, 2023). "Considering that knocking down STAG2 in BRAF-mutant melanoma cells significantly decreased their sensitivity to BRAF/MEK inhibitors, we thus attempted to determine whether STAG2 knockdown affected the response of BRAF-mutant thyroid cancer cells to BRAF/MEK inhibitors." (PMID 37479689, 2023). "Furthermore, we utilized a combination of functional enrichment- and gene expression-derived scores to model and identify pathways, such as HMOX1-mediated mitochondrial stress response, as potential key drivers of the emergence of a BRAF/MEK inhibitor-resistant state in melanoma cells." (PMID 37176114, 2023). "Thus, targeting USP5 offers a potential therapeutic strategy for BRAF inhibitor-resistant melanoma." (PMID 36694209, 2023). "Enhanced glycolysis (Warburg effect) driven by the BRAF oncogene, dysregulated GAPDH expression, and activation of the PI3K/AKT/mTOR signaling pathway may significantly contribute to the resistance-targeted therapy of BRAF-mutated melanomas." (PMID 37895015, 2023). "Here, we sought to test the hypothesis that the antitumor efficacy induced by the combinatorial use of BRAFi and VEGFA removal, BRAF/VEGFA targeting, correlates with the ability to induce an immune‐stimulatory milieu in a mouse syngeneic melanoma tumor model, derived from BRAF mutated murine cells." (PMID 37183363, 2023). "However, the considerations in choosing BRAF/MEK or anti-PD-1 as first-line therapy in the advanced melanoma setting (i.e., relatively quick anti-tumor effect of BRAK/MEK inhibitors versus less acquired resistance in case of immunotherapy) can be different in the adjuvant setting." (PMID 36672358, 2023). "Moreover, there have been reports of increased invasion in melanoma cells due to increased p38/MK2 activity, but this could be strongly linked to the use of BRAF-mutant cells while investigating the effects of p38." (PMID 36765834, 2023). "NF1/RAS deregulation in glioma class III mutations might be, as in melanoma or lung cancers, a way to resist to molecules inhibiting BRAF, but no recent publications link specific alterations to their therapeutic responses." (PMID 36831610, 2023). "It has been well established that BRAF p.V600E mutation drives the activation of the MAPK signaling pathway and that BRAF is frequently mutated in different cancer types, including leukemia, melanoma, thyroid carcinoma, colorectal adenocarcinoma, glioblastoma, and non-small-cell lung cancer." (PMID 36672445, 2023). "Furthermore, we showed that these PHB ligands can induce cell apoptosis via the loss of mitochondrial potential (MMP) and caspase activation in many melanoma cells irrespective of BRAF/NRAS mutation status." (PMID 37508519, 2023). "Patient 2 was a 52-year-old man, with stage-IV melanoma of unknown origin, BRAF-wildtype." (PMID 35841421, 2023). "The median age of melanoma patients (n = 101) receiving non-adjuvant, first-line systemic anti-PD-1-based therapy was 68 years; 63% were men, and 27% of the tumours had an oncogenic mutation in the BRAF gene." (PMID 37295047, 2023).
melanoma (continued). "Moreover, for BRAF wild-type melanomas, current recommendations advocate using monoclonal antibodies (i.e., ipilimumab) that target immunological checkpoint proteins such as anti-PD-1 or CTLA-4 (cytotoxic T-lymphocyte antigen 4) in combination with anti-PD-1 therapy." (PMID 36747120, 2023). "In addition, activation of the HGF‐MET pathway has been reported as a clinically relevant resistance mechanism in a variety of tumors, including trastuzumab resistance in HER2‐positive breast cancer, BRAF inhibitor resistance in melanoma, and bevacizumab resistance in glioblastoma." (PMID 36416133, 2023). "Thus, to assess the impact of GALC in human melanoma in a more relevant BRAF-mutated background, we investigated the effect of GALC overexpression on the proteomic landscape of A2058 and A375 human melanoma cells harboring the BRAF(V600E) mutation." (PMID 37445731, 2023). "Our data suggest that ICI may be less efficacious in BRAF V600E variant melanoma brain metastases but do not address the question of whether targeted therapy (combination BRAF and MEK inhibition) might be preferred to ICI in this patient population." (PMID 37589977, 2023). "However, BRAF/NRAS-activating mutations are less frequently mutated in MM compared to CM: 6% and 8%, respectively, versus 50% and 28% in CM, with a variable incidence depending on the anatomical district of melanoma occurrence." (PMID 37773078, 2023). "PAK1 inhibitor may have a prominent role in the treatment of melanoma with wild-type BRAF cells." (PMID 36830998, 2023). "Thus, increased AR expression in melanoma cells subverts the transcriptional response of melanoma cells to BRAF inhibition, with suppression of pro-apoptotic, immunomodulatory, and antigen presentation pathways and enhancement of pathways implicated in tumor progression and BRAFi resistance." (PMID 37838724, 2023). "Thus, it is critical to investigate further the effects of BRAF on the pathogenesis of melanoma." (PMID 37205993, 2023). "In addition, patients with or without BRAF-mutated melanoma, as well as those with acral and mucosal melanoma, a high tumour burden, or M1a/b baseline metastases, all benefit from nivolumab plus relatlimab versus nivolumab alone." (PMID 37072748, 2023). "Following recent observations from clinical trials indicating that patients with BRAF-mutant melanoma in particular benefit from dual ICI1–3, we wondered whether we could derive a molecular rationale that prospectively leads to a more general biomarker concept for ICI therapy stratification." (PMID 37525015, 2023). "In particular, this review has described the impact of BRAF mutational status on melanogenesis through a mechanism strictly related to MITF, since MITF-mediated increase in melanogenesis enzymes and melanosomal markers represent key players in melanoma progression." (PMID 37627054, 2023). "Furthermore, targeting BRAF in other cancer types harboring the BRAF V600E mutation has not been as effective as in melanoma, suggesting that these cancers are intrinsically resistant to BRAF inhibition." (PMID 38136350, 2023). "PD-L1 expression is independent of melanoma driver mutation status (BRAF/RAS/NF1)." (PMID 37239381, 2023). "In fact, a low mutation rate of BRAF was observed in acral melanomas than in non-acral melanomas." (PMID 37627054, 2023). "Finally, voruciclib, one of the CDK4/6i with anticancer effects, in combination with the BRAF inhibitor vemurafenib in advanced BRAF-mutant melanoma or with the proteasome inhibitor bortezomib in TNBC xenografts was found to antagonize ABCB1- and ABCG2-mediated multidrug resistance in cancer cells." (PMID 37835528, 2023). "PTPN11 missense and short insertion‒deletion variants have been reported in 58 of 1,030 (6%) melanoma samples in the COSMIC database (including two of the variants we describe in this study), and PTPN11 has recently been implicated in the pathogenesis of BRAF-wild-type melanoma." (PMID 36566878, 2023).
melanoma (continued). "Similarly, we assessed targeted therapy in melanoma, specifically BRAF and MEK inhibitors." (PMID 36949413, 2023). "Thus, this rigid collagen-rich matrix will confer resistance of melanoma cells to BRAF inhibitors." (PMID 37174072, 2023). "However, it is still not fully understood whether other novel transcriptional factors and programs act downstream of BRAF(V600E) in the regulation of melanoma progression." (PMID 37760480, 2023). "Moreover, melanoma cells maintain the high glycolytic profile by activating the MAPK and (PI3K)/ Akt/mTORC1 signaling pathways (by means of V600E mutation activation in BRAF gene or PTEN inactivation) by competing with effector T cells for glucose." (PMID 38435479, 2023). "Therefore, we wondered whether targeting EZH2 might represent a new therapeutic option in melanomas resistant to BRAF inhibitors." (PMID 36768289, 2023). "Therefore, the objective of this study was to estimate the cost-effectiveness of a combination treatment of BRAF plus MEK inhibitors with or without ICI treatments as a first-line adjuvant treatment for BRAF-mutant advanced melanoma from the US payer perspective." (PMID 36653848, 2023). "While BRAF mutation alone may not contribute to the formation of melanoma, driver mutations in the tumor suppressor genes are frequently required for malignant melanoma progression." (PMID 36649046, 2023). "Interestingly, the observation that a genetically induced reduction in TFEB level increased the antiproliferative effect exerted by a BRAF inhibitor suggests new possible therapeutic interventions targeting TFEB for managing melanoma and overcoming acquired resistance to standard therapies." (PMID 37160873, 2023). "Furthermore, we found that TCF12 depletion sensitizes melanoma cells to BRAF inhibition, suggesting that TCF12 may represent a potential therapeutic target for enhancing the efficacy of current BRAF-targeted therapies." (PMID 37760480, 2023). "For example, only patients with class 1 BRAF-mutant melanomas respond to current targeted therapy agents, and acquired resistance invariably occurs, which may also confer cross-resistance to immunotherapy through MAPKi-driven phenotype switching/dedifferentiation." (PMID 37616051, 2023). "One of the most recent options for melanoma treatment is targeted therapy, being the combination of BRAF (V-RAF murine sarcoma viral oncogene homolog B) and MEK (mitogen-activated protein kinase kinase) inhibitors used to enhance survival in BRAF-mutated patients." (PMID 37049869, 2023). "In locally advanced (stage III) or resectable metastatic (stage IV) melanomas, medical adjuvant treatment is proposed and recent advances had shown the benefit of anti-PD1/PDL1 and anti-CTLA4 immunotherapy as well as anti-BRAF and anti-MEK targeted therapy in BRAF V600 mutated tumors." (PMID 37328818, 2023). "A correlation was observed between reduced plasma levels of four specific EV-melanoma membrane-bound proteins (MCSP, MCAM, ERBB3 and LNGFR) and response to treatment involving combination BRAF/MEK inhibitors in patients with metastatic disease harbouring the BRAF V600E mutation." (PMID 38201222, 2023). "At present, we do not know whether the effects observed in BRAF-mutated human melanoma cells following GALC overexpression are due to an excess of enzyme product(s) and/or a reduction in its substrate(s)." (PMID 37445731, 2023). "The phase III randomized trial, DREAMseq (Doublet, Randomized Evaluation in Advanced Melanoma Sequencing), compared the efficacy and toxicity of nivolumab/ipilimumab followed by dabrafenib/trametinib to the converse sequence progression in 265 patients with advanced BRAF V600-mutant melanoma." (PMID 36995534, 2023). "This may indicate that the synergistic effects seen of intratumoral poly(I:C) with checkpoint blockade and BRAF inhibition in mouse models of melanoma may be at least partially due to the increased activation of antigen bearing mDC and rDC within the lymph node." (PMID 37478193, 2023).